ICAM1 (intercellular adhesion molecule 1)
Diseases named in the same sentence as ICAM1 in open-access papers (continued):
Sharing a sentence is not in itself a finding about the gene and the disease.
abscess (2 papers, 2007 to 2025). An inflammatory process characterized by the accumulation of pus within a newly formed tissue cavity which is the result of a bacterial, fungal, or parasitic infection or the presence of a foreign body. "Neutrophils in UC show impaired Intercellular Adhesion Molecule 1 (ICAM-1) suppression, driving recruitment and abscess formation, and reduced anti-inflammatory signaling due to decreased lipoxin A4 (LXA4), which normally limits neutrophil migration." (PMID 41148805, 2025). "The vessels in an abscess express enhanced levels of adhesion molecules like ICAM-1 (intercellular cell adhesion molecule) and PECAM (platelet endothelial cell adhesion molecule) which are not expressed in the normal brain and are thought to be involved in guiding the immune cells to the abscess." (PMID 18030336, 2007).
acute liver failure (2 papers, 2019 to 2020). Rapid deterioration of liver function causing encephalopathy and coagulopathy. "Analysis of human genes of primary human hepatic sinusoidal endothelial cells and patient tissues after APAP overdose induced acute liver failure showed that ICAM1 and EDN1 obviously increased, further supporting our findings." (PMID 32550899, 2020). "In contrast, levels of HGF, LIF, M-SCF, VCAM, and ICAM1 were highest for acute liver failure (ALF) and lowest for tumor patients, indicating that tissue damage plays the largest pathophysiological role in patients with ALF." (PMID 30740106, 2019). "In patients with acute liver failure (ALF), levels for HGF, ICAM-1, and IFN-α2 were found to be elevated compared to patients with biliary atresia or liver tumor patients." (PMID 30740106, 2019).
airway allergies (2 papers, 2016 to 2022). "Bronchial epithelial cells act as immunoregulators in allergic respiratory diseases through the expression of adhesion molecules on the cell surface, such as ICAM1." (PMID 35057008, 2022).
alcoholic hepatitis (2 papers, 2018 to 2024). Acute hepatitis resulting from ingestion of alcohol. "This important finding reflects that monocytes in alcoholic hepatitis are primed for binding to adhesion molecules expressed by the endothelium, i.e., ICAM-1." (PMID 29904132, 2018).
alpha-synucleinopathy (2 papers, 2024). "Finally, in order to overcome interference of non-AD copathology on BBM interpretation, VCAM1/ICAM1 and alpha-synuclein are emerging in research as new BBMs suitable for the identification and characterization of non-AD copathology such as vascular pathology and alpha-synucleinopathy, respectively." (PMID 39684623, 2024).
anorexia nervosa (2 papers, 2010 to 2021). A disorder most often seen in adolescent females characterized by a refusal to maintain a minimally normal body weight, an intense fear of gaining weight, a disturbance in body image, and, in postmenarcheal females, the development of amenorrhea. "The link between the kynurenine pathway and immunomodulatory molecules—fractalkine and soluble intercellular adhesion molecule-1 (sICAM-1)—in anorexia nervosa (AN) remains unknown." (PMID 33498837, 2021).
Ascites (2 papers, 2015 to 2025). Accumulation of fluid in the peritoneal cavity (between the layers of the peritoneum that lines the abdomen). "In ascites, low VCAM-1 and ICAM1- levels showed an association with surgeries exceeding 336 minutes whereas only VCAM1 has significant association." (PMID 40652770, 2025).
atrial fibrillation (2 papers, 2024). A disorder characterized by an electrocardiographic finding of a supraventricular arrhythmia characterized by the replacement of consistent P waves by rapid oscillations or fibrillatory waves that vary in size, shape and timing and are accompanied by an irregular ventricular response. "In a cohort of 2434 women, a significant relation between inflammatory markers such as CRP, fibrinogen, and soluble intercellular adhesion molecule-1 and new onset atrial fibrillation at a median follow-up of 14.4 years was proven." (PMID 38672728, 2024).
bacteremia (2 papers, 2010 to 2018). "In our study, we found six of the soluble mediators analyzed that differentiated between patients with and without bacteremia: TNF-α, CCL4, TIMP-1, VCAM-1, ICAM-1, and E-selectin." (PMID 29681903, 2018). "Using unsupervised hierarchical clustering, we found that TNFα, CCL4, E-selectin, VCAM-1, ICAM-1, and TIMP-1 could be used to discriminate between patients with and those without bacteremia." (PMID 29681903, 2018).
bone cancer (2 papers, 2017 to 2024). A primary or metastatic malignant neoplasm affecting the bone or articular cartilage. "ICAM-1 expression is associated with the migration and invasion of breast, lung, gastric, oral, and bone cancer cells." (PMID 28903329, 2017). "Therefore, ICAM-1 is a potential therapeutic target for bone tumors." (PMID 28903329, 2017).
bronchitis (2 papers, 2017 to 2024). An acute or chronic inflammatory process affecting the bronchi. "Moreover, higher ICAM-1 protein expression was reported in the basal cells of bronchial epithelium from individuals with “bronchitis”, compared to normal individuals, but sputum concentrations of sICAM-1 did not significantly correlate with FEV1." (PMID 28056984, 2017).
bronchopulmonary dysplasia (2 papers, 2021 to 2024). Bronchopulmonary dysplasia is a chronic respiratory disease that results from complications related to lung injury during the treatment of infant acute respiratory distress syndrome in low-birth-weight premature infants or from abnormal lung development in older infants. "Moreover ICAM-1 levels in plasma were associated with bronchopulmonary dysplasia (BPD) severity and outcome, while also serum levels were an indicator of perinatal asphyxia." (PMID 34065912, 2021).
Cachexia (2 papers, 2019 to 2025). Severe weight loss, wasting of muscle, loss of appetite, and general debility related to a chronic disease. "Cluster 6 also included marker genes indicative of endothelial inflammation/dysfunction and increased vascular permeability (e.g., Selp, Icam1, Vcam1) which were elevated prior to cachexia development." (PMID 39810606, 2025). "Consistent with prior studies, KxPxCx allograft-induced cachexia resulted in hypothalamic inflammation in vehicle-treated animals, with increases in expression of Selp, Il1b, Il1r1, Tlr7, Ccl2, and Icam1." (PMID 31615993, 2019).
Chronic colitis (2 papers, 2019 to 2024). A chronic inflammatory disease of the large intestine (colon, cecum and rectum). "The third objective was to examine the involvement of the intercellular adhesion molecule-1 (ICAM-1) and lymphocyte function-associated antigen-1 (LFA-1) in the formation of plexitis in vivo using the Winnie mouse model of spontaneous chronic colitis." (PMID 38428588, 2024).
chronic heart failure (2 papers, 2015 to 2016). "In fact, soluble ICAM-1 has been shown to be upregulated in patients with chronic heart failure and a significant negative correlation between left ventricular ejection fraction and soluble ICAM-1 levels has been observed." (PMID 25821551, 2015). "In patients suffering from CAD and congestive heart failure, daily ingestion of flavanol-rich chocolate or cocoa for 28–42 days did not change CRP, P-selectin, E-selectin, ICAM-1, or VCAM-1." (PMID 27240397, 2016).
coronary artery calcification (2 papers, 2017). Calcification of the coronary artery, used as a measure of coronary atherosclerosis, a risk factor for myocardial infarction. "Number of circulating tissue factor, intercellular adhesion molecule-1, stem cells, and adipocytes antigen positive blood-borne MV associated with coronary artery calcification in postmenopausal women with histories of PE." (PMID 28910282, 2017).
dermatomyositis (2 papers, 2015 to 2025). Dermatomyositis (DM) is a type of idiopathic inflammatory myopathy characterized by evocative skin lesions and symmetrical proximal muscle weakness. "• Dermatomyositis (DM) patients had higher circulating ICAM-1 and VCAM-1 levels compared to healthy controls." (PMID 40055821, 2025). "However, the positive clinical effects of high-dose IVIG on muscle function in patients with refractory inflammatory active myositis in the form of polymyositis or dermatomyositis are not accompanied by any effects on ICAM-1 and VCAM-1." (PMID 26714881, 2015).
disc degeneration (2 papers, 2017 to 2018). "Targeting the CCL2/ICAM1 pathways may be pivotal in the preventive treatment of inflammatory responses that aggravate the process of disc degeneration." (PMID 30585203, 2018). "The enhancement of CCL2-dependent ICAM1 expression occurs through the JAK1/FAK/ERK/GSK3 and PKCδ signaling pathways in AF cells, which may contribute to immune cell recruitment and disc degenerative diseases." (PMID 30585203, 2018).
Disseminated intravascular coagulation (2 papers, 2012 to 2017). Disseminated intravascular coagulation is characterized by the widespread activation of coagulation, which results in the intravascular formation of fibrin and ultimately thrombotic occlusion of small and midsize vessels. "It is also responsible of an increased expression of the intercellular adhesion molecule-1 (ICAM-1) by endothelial cells, representing a possible predictor of disseminated intravascular coagulation." (PMID 22762008, 2012).
esophageal adenocarcinoma (2 papers, 2013 to 2020). A malignant tumor with glandular differentiation arising predominantly from Barrett mucosa in the lower third of the esophagus. "TGF-β1 is an endogenous radioresistance factor in the esophageal adenocarcinoma and the expression of ICAM1 is affected by IR." (PMID 24367666, 2013).
fetal growth restriction (2 papers, 2021 to 2023). A fetus that does not grow beyond the 10th percentile of conventionally accepted weight for gestational age. "Increased levels of ICAM-1 have been found in the placentas of women with pre-eclampsia, and the molecule has been implicated in the pathogenesis of fetal growth restriction." (PMID 37299395, 2023). "Levels of ICAM-1, VCAM-1, and E-selectin were significantly higher in women with preeclampsia and IUGR (intrauterine growth restriction)." (PMID 34065912, 2021).
fibrosarcoma (2 papers, 2016 to 2019). A malignant mesenchymal fibroblastic neoplasm affecting the soft tissue and bone. "In the T241 fibrosarcoma model, there was a high expression of ICAM-1 and VCAM-1 in the tumor vasculature in control mice." (PMID 27385210, 2016).
focal segmental glomerulosclerosis (2 papers, 2010 to 2022). A renal disorder characterized by sclerotic lesions in the glomeruli. "Where ICAM-1 and P-selectin were present, primarily CD4+ T cells were also detected, except in two cases of focal segmental glomerulosclerosis and in one case of membranoproliferative glomerulonephritis." (PMID 20459816, 2010).
Follicular thyroid papillary carcinoma (2 papers, 2023 to 2024). "A growing amount of evidence has suggested that B7-H3 and ICAM-1 are upregulated in papillary thyroid carcinoma." (PMID 38858715, 2024). "Via bioinformatics analysis and experimental validation, MET and ICAM1 were found to be upregulated in lymph node metastasis from papillary thyroid carcinoma." (PMID 37274228, 2023). "Via bioinformatics analysis and experimental validation, the expressions of MET and ICAM1 were found to be upregulated in patients with lymph node metastasis from papillary thyroid carcinoma." (PMID 37274228, 2023). "Furthermore, the patients with Stage2, 61-80y, Follicular thyroid papillary carcinoma and N0 had lower B7-H3 and ICAM-1 mRNA expression." (PMID 38858715, 2024).
gastritis (2 papers, 2023 to 2024). Inflammation of the stomach. "These investigators observed over-expression of ICAM-1 and TNF-α genes at the early stages of IND-induced gastritis." (PMID 38652367, 2024).
giant cell arteritis (2 papers, 2020 to 2025). "Additionally, levels of soluble intercellular adhesion molecule-1 (sICAM-1), a marker of large vessel vasculitis activity, as seen in giant cell arteritis and Kawasaki disease, are correlated with the clinical phase of carotidynia." (PMID 40225483, 2025).
Glucose intolerance (2 papers, 2020 to 2022). Glucose intolerance (GI) can be defined as dysglycemia that comprises both prediabetes and diabetes. "Changes in cholesterol levels due to glucose intolerance induce dysregulation of ICAM-1 and VCAM-1." (PMID 36297290, 2022).
gonococcal infections (2 papers, 2020 to 2024). "In addition to CXCL8 and IL1B, we also observed multiple genes previously shown to be involved in responses to gonococcal infections, including PTGS2 and ICAM1." (PMID 38976720, 2024).
Graves’ orbitopathy (2 papers, 2014 to 2019). "Hence, detection of HLA-DR and ICAM-1 molecules on the conjunctiva may suggest activity of the immunopathological process underlying Graves' orbitopathy which should be considered as an indication of intensive systemic immunosuppression." (PMID 24562464, 2014). "The percentage of HLA-DR+ and ICAM-1+ conjunctival epithelial cells in patients with the active GO may serve as a topical inflammation marker in Graves’ orbitopathy." (PMID 24562464, 2014).
H1N1 virus infection (2 papers, 2013 to 2017). "In our current study, analyses of cellular adhesion molecule expression on A549 in response to H1N1 virus infection revealed an upregulation of ICAM-1, VCAM-1, and E-selectin; this is subsequently inhibited by TSL-1." (PMID 24073006, 2013).
hepatitis B (2 papers, 1995 to 2020). "LFA-1 binds ICAM-1 (intercellular adhesion molecule-1), and LFA-1–ICAM-1 interaction has long been identified as critical for T cell infiltration into the liver in hepatitis B infection." (PMID 32560123, 2020).
hypertrophic cardiomyopathy (2 papers, 2013 to 2026). A condition in which the myocardium is hypertrophied without an obvious cause. "ICAM-1 and VCAM-1 are upregulated in EC after Gb3 stimulation, and VEGF has been associated with hypertrophic cardiomyopathy in FD patients." (PMID 41545379, 2026).
hypervitaminosis A (2 papers, 2017 to 2018). A symptom complex resulting from ingesting excessive amounts of vitamin A. "Quantification showed an approximately 5-fold increase of Icam1- positive cells in hypervitaminosis A compared to controls." (PMID 28426756, 2017). "Circulating levels of soluble Icam1, also a factor associated with inflammation and endothelial damage, were not altered during the initial 2 days of hypervitaminosis A." (PMID 30003121, 2018). "Next, staining for Icam1, a key endothelial molecule involved in active recruitment and transendothelial migration of preosteoclasts from the blood, revealed increased staining in hypervitaminosis A animals." (PMID 28426756, 2017).
interstitial cystitis (2 papers, 2014 to 2020). A rare chronic debilitating urogenital disease characterized by urinary frequency, urgency, and pelvic pain. "It has been shown that expression of ICAM-1 is increased in bladder biopsies from patients with interstitial cystitis (IC), but undetectable in non-pathological bladder biopsies." (PMID 25354343, 2014).
ischemic limb disease (2 papers, 2015 to 2022). "In conclusion, in PMBCs from clinical coronary CTO patients and a rat model of hind limb ischemia, an elevated survivin expression in PBMCs, particularly of survivin and CD8, VEGF, ICAM-1 double-positive PBMCs were associated with good collateral formation." (PMID 25816072, 2015).
keratitis (2 papers, 2017 to 2021). A corneal disease that is characterized by inflammation of the cornea. "keratitis as compared to normal mice, which results in vasodilation, increased intercellular adhesion molecule-1 (ICAM-1) expression on endothelial cells, and neutrophil infiltration." (PMID 34685489, 2021). "H-RN inhibited IL-6, monocyte chemotactic protein-1(MCP-1), Interferon- γ(IFN-γ), and ICAM-1 expression triggered by LPS or poly(I:C), alleviated the clinical manifestation and reduced the clinical score in keratitis in vivo." (PMID 28125988, 2017).
keratoconus (2 papers, 2016). A degenerative, structural disorder of the eye, characterized by a cone-shaped protrusion of the cornea. "A presumed progression risk factor of keratoconus is the contact lens wear, especially rigid gas permeable contact lenses that induce the upregulation of IL-6, TNF-alpha, ICAM-1, and VCAM-1 in the tears of subjects with keratoconus." (PMID 27563164, 2016). "Albeit, recent studies have shown that matrix metalloproteinases MMP1 and 9, AZGP1, SFRP1, IGKC and cell adhesion molecules ICAM-1 and VCAM-1 to be specifically regulated in keratoconus, indicating their probable exclusive role in keratoconus." (PMID 27493978, 2016).
kidney cancer (2 papers, 2016 to 2022). Primary or metastatic malignant neoplasm involving the kidney. "We found up-regulation of uc010xle/AK301412 ICAM1 alternative splice isoform in colorectal, breast, prostate, and kidney cancers that may be important prognostic factor." (PMID 28105922, 2016). "The overexpression of SIGIRR in RCC cells attenuated IL1-induced NFKBIZ activation, with a trend of effect on IL6, PD-L1, and ICAM1 induction, suggesting that SIGIRR manipulation may be beneficial to block IL1 in kidney cancer." (PMID 35814450, 2022).
leukocyte adhesion deficiency (2 papers, 2004 to 2014). Leukocyte adhesion deficiency (LAD) is a primary immunodeficiency characterized by defects in the leukocyte adhesion process, marked leukocytosis and recurrent infections. "However, this phenomenon has also been previously reported in CD18, P-sel/ICAM-1 mutant mice, and in patients with moderate or severe leukocyte adhesion deficiency." (PMID 15274743, 2004).
lichen planus (2 papers, 2012 to 2013). A chronic, recurrent, pruritic inflammatory disorder of unknown etiology that affects the skin and mucus membranes. "In the present study, VCAM1 and ICAM1 expression was significantly higher in lichen planus in comparison to normal mucosa." (PMID 24551788, 2013). "Wilcoxon test also revealed higher ICAM1 expression in lichen planus compared to normal mucosa in 29 cases and in one case, ICAM1 was found to be equal in lichen planus and normal mucosa." (PMID 24551788, 2013). "In total, difference in ICAM1 expression was significant between lichen planus and normal mucosa (p<0.001)." (PMID 24551788, 2013). "Likewise, in the present study, a significant increase has been found in ICAM1 expression in lichen planus compared to normal mucosa, indicating the importance of ICAM1 in leukocyte migration from blood circulation to oral tissues." (PMID 24551788, 2013). "Also, ICAM1 expression between lichen planus and normal mucosa, showed a significantly difference (p<0.001)." (PMID 24551788, 2013). "The mentioned-above reasons can justify the increment in the number of leukocytes in superficial connective tissue in the form of band-like inflammatory infiltrates in lichen planus, so as increase in ICAM1 expression can be considered as a reason for an increased leukocytes number." (PMID 24551788, 2013). "Regarding the fact that VCAM1 and ICAM1 are expressed by endothelial cells and leukocytes, the increase of their expression can be attributed to the increase in blood vessels and leukocytes in lichen planus." (PMID 24551788, 2013). "Up-regulation of intercellular adhesion molecule-1 (ICAM-1) and cytokines associated with Th 1 immune response, such as interferon (IFN)-gamma, tumour necrosis factor (TNF)- alpha, interleukin (IL)-1 alpha, IL-6 and IL-8, may also play a role in the pathogenesis of lichen planus." (PMID 22980383, 2012).
Lymphadenopathy (2 papers, 2016 to 2021). Enlargement (swelling) of a lymph node. "In patients having lymphadenopathy, CLL cells are able of collecting prosurvival signals through αLβ2 and α4β1 integrins linked to ICAM-1 and VCAM-1 mediated diapedesis." (PMID 27374180, 2016).